CD4 (CD4 molecule)
Diseases named in the same sentence as CD4 in open-access papers (continued):
Sharing a sentence is not in itself a finding about the gene and the disease.
tumor (continued). "We examined the CD4+ and CD8+ T lymphocytes of the tumor tissues by immunohistochemical fluorescence experiments of the paraffin sections." (PMID 38445883, 2024). "IL‐2‐Fc and ICK caused significant decreases in circulating CD4+ T cells in both models, although no significant changes in circulating Tregs were observed in both models, suggesting changes in circulating T cell frequencies do not correlate with changes seen within the tumor." (PMID 38317590, 2024). "Consistently, the infiltration levels of those anti-tumor immune cells were significantly decreased in the ZMIZ2 high expression groups, while the infiltration scores of CD4 T cells and DCs were higher." (PMID 38254216, 2024). "The expression of CD3, CD4 and CD8 in tumour-infiltrating T lymphocytes were localised to the plasma membrane." (PMID 38816839, 2024). "Recombinant Newcastle disease virus strains expressing cytokines such as IL-2, IL-15, or TRAIL stimulate tumor-specific CTL responses, inducing CD4+ and CD8+ T cell proliferation, leading to tumor regression." (PMID 38731910, 2024). "We did not observe a significant change in the proportions of naive or memory CD4 and CD8 T cells, likely due to the weak immunogenicity of this model at baseline and low infiltration of T cells in the tumor microenvironment." (PMID 39044819, 2024). "These frequencies remained consistent across all conditions, which is crucial as both CD4 and CD8 T cells contribute to anti-tumor activity." (PMID 39364400, 2024). "This enhances the infiltration of effector T cells (CD4+ and CD8+ T cells) into the tumor, promoting the release of pro-inflammatory cytokines (TNF-α, IL-6, and IL-12), killing the cancer and reversing tumor resistance." (PMID 39004737, 2024). "Utilizing a mxIF panel of CD4, CD8, FOXP3, PD-1, Ki-67, and synaptophysin; T cells were appreciated throughout the tumor microenvironment of ONB." (PMID 38822345, 2024). "Partition-based graph abstraction (PAGA) trajectory analysis of CD4+ and CD8+ TCR135pos clusters confirmed a developmental trajectory from day 0 enriched clusters to day 7 tumor-enriched clusters." (PMID 38412034, 2024). "Deletion of NRP1 in both CD4+ and CD8+ T cells enhance CD8+ T-cell infiltration into tumours and restricted tumour growth in animal models." (PMID 38609390, 2024). "For instance, regulatory T cells (T-reg cells) have vital immunosuppressive functions, which regulate the activation and differentiation status of CD4+ or CD8+T cells and impede anti-tumor immune defenses, boosting tumor development and metastasis." (PMID 38357546, 2024). "In line with this idea, we observed that CD4 TILs displayed stronger effector functions in the TME of C-225, consistent with prior studies showing a role of CD4 T cells in anti-tumor immunity." (PMID 39055715, 2024). "Transitioning to another facet of the tumor microenvironment, Tregs play a critical role in inhibiting various immune cells, including CD8+ and CD4+ T cells, dendritic cells, and NK cells." (PMID 39664377, 2024). "LAG3, often expresses on the lymphocytes, including CD4+ T cells, NK cells, CD8+ T cells, and Treg cells, impeding the tumor immune microenvironment through accelerating T cell exhaustion and blocking T cell proliferation." (PMID 39872538, 2024). "Firstly, IL-12 can activate T cells and NK cells to drive Th1 differentiation of CD4+ T cells via enhanced production of IFN-γ and augments the cytolytic ability of NK and CD8+ T cells towards tumor cells via granzyme B and perforin secretion." (PMID 38548896, 2024). "Analysis of tumor immune cell composition after 4 days of RMC-6236 administration showed a significant increase of CD4+ and CD8+ T cells in the tumor microenvironment (TME), relative to tumors from vehicle controls." (PMID 38593348, 2024).
tumor (continued). "Overall, this data suggests that many of the proteins we identified in the chronic T-cell stimulation model are likewise elevated in vivo in exhausted CD4+ (and often simultaneously in exhausted CD8+) T cells in a tumor context." (PMID 39689157, 2024). "Previous research has suggested that there are multiple tumor-infiltrating immune cells in UM, such as CD8+ T-cells, CD4+ Treg, and macrophages." (PMID 39109337, 2024). "ProAgio reduces CD4+ Treg and Myeloid-derived suppressor cells (MDSCs), increases CD8+ T-cells, and increases the M1/M2 macrophage ratio in the tumor." (PMID 39001545, 2024). "In a recent study, CD4+ T cells combined with effector CD8+ T on the same DC cells to form a three-cell-type cluster to promote the toxicity of CD8+ T cells and eliminate tumor cells." (PMID 39372416, 2024). "Increased MDSCs in turn create a permissive tumour microenvironment via antagonistic actions on antitumor CD8+ and CD4+ T cells." (PMID 38750176, 2024). "Statistically significant differences were seen between iron and CD4+CD3+ T lymphocytes; CD4/CD8 ratio; CD4+CD69+ tumor; CD4+CD25+ tumor; CD8+PD-1 tumor; CD3+CD25+ node T lymphocytes; and CD19+PD-1 node B lymphocytes." (PMID 38256645, 2024). "We furtherly double-stained macrophages (CD163+ CD68+), helper T cell (CD3+ CD4+), cytotoxic T cell (CD3+ CD8+), and Treg cell (CD4+ FOXP3+) of subcutaneous tumor tissues and examined the cells using immunofluorescence (IF)." (PMID 38483163, 2024). "Anti-CTLA-4 Ab treatment resulted in recruitment of interferon-gamma (IFN-g)-producing CD4+ T cells, called T-helper 1 (Th1), into tumors, and neutralization of IFN-g abrogated the anti-tumor effects." (PMID 39106430, 2024). "Conversely, in the tumor tissues derived from mice implanted with LLC‐PRPS2 cells, we observed a significant decrease in the percentage of CD4+ T cells and CD8+ T cells, coupled with a significant increase in the percentage of TAMs, M‐MDSC, and PMN‐MDSC." (PMID 38952044, 2024). "OBP-702 exhibited a marked antitumor effect against murine OS by inducing the tumor infiltration of CD8+ and CD4+ T cells." (PMID 39108499, 2024). "The expression of these chemokines resulted in CD4+ and CD8+ T-cell infiltration, tumor control, and patient survival." (PMID 38360737, 2024). "In the invasive margin of CRC liver metastasis (CRC-L), CCL5+CD4 and CD8 cells, recruited by myeloid-derived CXCL9 and CXCL10, attract macrophages promoting invasion and tumor growth by MMP." (PMID 39100682, 2024). "On the one hand, tumor-infiltrating neutrophils express a protein called PD1 ligand PDL1, which hinders the function of CD4+ and CD8+T cells by binding to PD1, and this interaction promotes the evasion of the immune system by the tumor." (PMID 38933262, 2024). "The 10 parameters that drive the classifier comprise: tumor area; density of CD4 T cells in tumor and stroma, and that of CD8 T cells in stroma; as well as the CD4-CD4; CD8-CD56; CD68-CD68; CD4-CK; CD68-CK; and CK-CK distances." (PMID 40604303, 2024). "Although γδ T cells are typically less abundant in tumors compared to CD4+ and CD8+ T cells, they possess a more potent tumor-killing ability." (PMID 39916962, 2024). "We examined the infiltration of CD4+ T cells and CD8+ T cells within the tumor microenvironment induced by aAGd-NWs+RT." (PMID 38724527, 2024). "The therapeutic effects of TCM in TNBC primarily involve immune modulation within the tumor microenvironment, particularly through the regulation of CD8+ and CD4+ T cells." (PMID 39867914, 2024). "CD8+ T cell-mediated tumor killing is regarded as a key for tumor regression, but recent research presented the essential role of Interferon (IFN)-γ-producing CD4+ T helper(Th)-1 cells in mediating long-term antitumor immune protection." (PMID 38827732, 2024). "As anticipated, they observed an increase in CD4+ and CD8+ T cells in the spleen and at distant tumor tissues, indicative of a systemic immune response." (PMID 38391959, 2024).
tumor (continued). "We showed that there was initially a relative paucity of tumor-infiltrating T cells; however, following CAIR treatment, there was a significant increase in CD4 and CD8 T cells with a significant decrease in Treg cells." (PMID 38731089, 2024). "The morphology of the tumor cells appeared blastic with an abnormal immunephenotype CD3+, CD2−, CD5dim, CD4−, CD8+, CD56−, and CD30−." (PMID 39091627, 2024). "Hepatic metastasis, tumor size ≥ 2 cm, CD3+AC < 898 cells/μL, CD4+AC < 498 cells/μL, CD8+AC ≥ 292 cells/μL and B AC ≥ 99 cells/μL were independent risk factors affecting PFS." (PMID 38833153, 2024). "The majority of NPC patients showed 50%–100% expression of HLA-DP on tumor cells, indicating that NPC is well suited for CD4 TCR-T therapy." (PMID 38412034, 2024). "One of the most significant indications for an anti-tumor immune response following AGI-134 treatment has been the infiltration of CD4+ T helper cells and of CD8+ cytotoxic T cells in 47% of the un-injected tumor lesions." (PMID 39458595, 2024). "Immunophenotyping of 3LL-ΔNRAS tumours treated for 7 days with the quadruple combination revealed increased infiltration and activation of CD8+ and CD4+ T cells." (PMID 39322643, 2024). "The immune cells of TME, mainly CD4+ and CD8+ tumor-infiltrating lymphocytes (TILs), suppress the proliferation of cancer cells and play a crucial role in the progression of OSCC." (PMID 38779258, 2024). "Similar to the homeostatic conditions, CD11c:DTA mice showed reduced or enhanced fractions of CD4+CD44+ T cells and CD8+CD44+ T cells or CD8+CD62L− T cells in Spl as compared with WT mice under tumor-bearing conditions." (PMID 39206204, 2024). "In the same line, flow cytometry of T cells confirmed higher expression of CXCR6 on CD8+ T cells relative to CD4+ T cells, in agreement with the observation that CD8+ T cells are especially segregated at the tumor margin in the immune-excluded model." (PMID 38509063, 2024). "Upon examining the distribution of the eight cell lineages, the most predominant cell type in the tumor samples was HCC, followed by macrophages, CD4+ T cells, and CD8+ T cells." (PMID 38577593, 2024). "This combination treatment diminished FOXP3 + Treg cell levels and elevated CD4 + and CD8 + T-cell levels (p < 0.05), significantly reducing tumor growth." (PMID 38956700, 2024). "Ablation of IL-17 resulted in accelerated tumor growth and more metastatic foci of tumors in subcutaneous inoculation of MC38 colonic-tumor mouse model, in which IFN-γ+ CD4+ and IFN-γ+ CD8+ T cells were decreased in tumor tissue." (PMID 39906741, 2024). "Lymphocytes such as CD4 + and CD8 + T cells can induce tumor cell apoptosis and inhibit tumor progression through immune-mediated cytotoxic activity." (PMID 38688967, 2024). "CD4+ T cells support this process by promoting the activation and growth of CD8+ T cells and can sometimes directly target tumor cells themselves, thus also playing a vital role in the efficacy of cancer immunotherapies." (PMID 38962016, 2024). "Recent research has identified key enzymes involved in CD4+ T cell differentiation and the Kennedy pathway—ETNK1, PCYT2, and SELENOI—suggesting a potential correlation between SELENOI and tumor immunity." (PMID 39669976, 2024). "There was a notable increase in tumor-infiltrating CD3+ T cells, CD4+ T cells and CD8+ T cells, indicating that mIL12 treatment significantly promotes T lymphocyte infiltration." (PMID 39584994, 2024). "CD4 + or CD8 + T cell clusters can give rise to tertiary lymphoid structures (TLS), which play a pivotal role in tumor-specific immune responses." (PMID 38918836, 2024). "The amplified immune response involves CD4+ and CD8+ T cells, which deliver cytotoxic actions against the tumor, signifying PDT’s role in inducing tumor specific adaptive immunity." (PMID 38646546, 2024).
tumor (continued). "They observed increased recruitment of CD3+ T lymphocytes, particularly CD4+ and CD8+ cells, from peripheral tumor margins to the tumor core under FLASH-IR compared with CONV-IR." (PMID 39479528, 2024). "CD4 T cells enhance the anticancer activity of CD8 T cells and macrophages, and prevent tumor growth." (PMID 38342956, 2024). "Characterizing this treatment effect, immunological analysis found a higher percentage of circulating CD4+ and CD8+ T cells and tumor-specific cytotoxic T cells." (PMID 38675812, 2024). "recently reported that repression of Satb1 in CD4 T cells promotes Tfh cell differentiation and intratumoral TLS formation, resulting in restricted tumor growth in mice." (PMID 39076974, 2024). "This outcome has been attributed largely to reduced tumor infiltration by myeloid cells and repolarization of MDSC toward an immunostimulatory phenotype, which was accompanied by elevated anti-tumor CD4+ and CD8+ T cell responses." (PMID 38334604, 2024). "It has been reported that the tumor microenvironment of ACSL4−/− animal models displays decreased infiltration of CD8+, IFNγ+CD8+, TNFα+CD8+, and CD4+ T cells compared to the tumor microenvironment of ACSL4+/+ animal models." (PMID 38778030, 2024). "Several studies have reported that in the tumor microenvironment, LAG3 is expressed on the surface of TILs (CD4+ and CD8+ T cells), including Treg cells, B cells, NK cells, NKT cells, plasmacytoid DCs (pDCs), and tumor-associated macrophages (TAMs)." (PMID 38255322, 2024). "The results indicated that the CD4+ and CD8+ T lymphocytes increased in the tumor tissues from the Lysenin group." (PMID 38445883, 2024). "HCS cells can precisely target the tumor microenvironment to minimize systemic toxicity, inducing an immune response by activating CD3+ and CD4+ T cells." (PMID 38751816, 2024). "APOC1 down-regulation induces the reduction of M2-TAMs, B cells, and CD4+ T cell levels in HCC, with simultaneous growth in M1-TAMs, NK cells, and CD8+ T cells restraining tumor growth and invasion." (PMID 39408564, 2024). "Tumor-infiltrating lymphocytes, including CD8+ T cells, CD4+ T cells, B cells, NK cells, and myeloid cells, displayed varying levels of infiltration, indicating dynamic interactions between our signature and immune cell infiltration." (PMID 38356715, 2024). "Dendritic cells (DCs) are trained antigen-presenting cells able to regulate anti-tumor immune responses by activating CD8+ and CD4+ T cells via MHC class I and II molecules, respectively." (PMID 39273502, 2024). "There was a significantly higher number and frequency of CD8+ T cells and CD4+ T cells expressing IFN-γ and Ki-67 in the tumor-draining LNs." (PMID 37917174, 2024). "The main players that support FL cells and maintain the GC structure are CD4+ T follicular helpers (TFH) and follicular dendritic cells (FDC), which by means of CD40L, IL-4, and IL-21 cytokine signaling, contribute to tumor survival and proliferation." (PMID 38697976, 2024). "Consistent with the previous results, compared with the Control group, MWA inhibited tumor growth, upregulated IL-21R expression on CD8 + T cells, CD4 + T cell, dendritic cells (DCs), and macrophages." (PMID 38833177, 2024). "Tumor cells in MEITL are typically CD3+, CD5−, CD7+, CD4−, TIA-1+, granzyme B+, perforin+, and CD103+." (PMID 39447336, 2024). "Immunofluorescence staining of tumor sections also led to consistent results, demonstrating that Ce6@PPC-aCD47+L treatment led to the most remarkable infiltration of CD8+ T and CD4+ T cells." (PMID 38560565, 2024). "The GC in these patterns is fully developed and proliferative, with rule interactions between CD4+ T and CD8+ T cells outside the GC and signs of immune attacking the tumor cells." (PMID 39080406, 2024). "Mice treated with the combination therapy had higher percentages of tumor‐infiltrating CD8+ T‐cells and CD4+ T‐cells in both injected and non‐injected tumors compared with mice treated with either control or 2′3′‐cGAMP." (PMID 38400597, 2024).
tumor (continued). "CD4+ T cells, also known as Helper T cells, and CD8+ T cells, also referred to as cytotoxic T cells, both have crucial functions in the context of anti-tumor immunity." (PMID 38420194, 2024). "Strikingly, CD4+ T cells and CD4+ Tregs were significantly increased in ST3Gal5 KO tumors, while percentages of CD8+ T cells and NK cells remained similar in both tumor types." (PMID 38785323, 2024). "In this study, we collected all tumor-infiltrating immune cells from the HNSCC scRNA-seq data and defined them as CD4+ T cells, CD8+ T cells, NK cells, circulating T cells, myeloid cells, and B cells." (PMID 38622125, 2024). "The enhanced infiltration of immune cells, including CD3, CD4, and CD8 T cells, within the tumor tissues indicated an immunostimulatory response triggered by the combination treatment." (PMID 39459546, 2024). "VVL-m12 therapy induced increased intratumoral infiltration of CD4+ and CD8+ T cells and was able to clear tumor at early time points via increased induction and infiltration of effector T cells and central memory T cells (TCM)." (PMID 39840061, 2024). "Additionally, CD4+ T cells that express the forkhead box P3 (FoxP3) transcription factor function as regulatory T (Treg) cells and either directly or indirectly induce immunosuppression, both promoting immune tolerance and actively inhibiting anti-tumor immune responses." (PMID 38672372, 2024). "A significantly decreased frequency of tumor-infiltrating CD8+ T cells was observed in the Id2fl/flCd4-Cre+ mice, but the frequency of CD4+ T cells was normal." (PMID 38287103, 2024). "While T cells play a crucial role in the early stages of cancer by surveilling and controlling tumor growth, they can transform into suppressive CD4+ and CD8+ Tregs after prolonged exposure to tumor cells." (PMID 39664195, 2024). "The vaccination also increased the proportion of CD4+ T cells expressing granzyme B and IFN-γ in tumor tissues, suggesting their contribution to the antitumor effect." (PMID 38355548, 2024). "In a mouse model with 4T1 tumor, 40&Dox@BSA displayed significant phototoxicity and induction of immune system, such as an increase in the T cells (CD4+ and CD8 + ) /Treg ratio." (PMID 39138299, 2024). "L19-mIL12 treatment, alone or in combination with Ruxolitinib, equally increased the density of CD4+ and CD8+ T cells within the tumor compared to the saline group." (PMID 38448543, 2024). "In addition, immune cell infiltration analysis by Tumor Immune Estimation Resources (TIMER) database and the Xiantao academic tool demonstrated that FUNDC1 expression was strongly associated with the infiltration of Th2, NK, Th17, Tem, pDC, neutrophil, MDSC, CD4+ T, and γδ T cells." (PMID 39668821, 2024). "elevated PD-1 was found in CD4+T cells and CD8+T cells in the tumor tissues compared with in the spleens." (PMID 38430390, 2024). "The use of L-fuc as a modulator of anti-tumor immunity is a novel concept which was previously shown to depend on the fucosylation of a tumor-expressed MHC class ll molecule and CD4+ T cells." (PMID 38646527, 2024). "Specifically, CD4+ and CD8+ T cells identify tumor antigens and have demonstrated their ability to trigger apoptosis in tumor cells." (PMID 39513114, 2024). "Meanwhile, it was further revealed that CD4+T cells, in conjunction with IFN-activated mononuclear phagocytes, collectively instigated an indirect inflammatory process resulting in tumor cell death.." (PMID 38327747, 2024). "We performed a multiplex mIHC staining on tissue sections from 18 samples in the study cohort, and simultaneous detection of CD4/CD8+ lymphocytes, CK+ tumor cells, PD1+ cells, Foxp3+ cells, and TCF1+ cells in the TME by Inform 2.6." (PMID 39009684, 2024). "Activated HLA DR and IL-2R CD4 + T cells were able to directly kill tumor cells by mediating MHC II, inhibiting tumor cell growth." (PMID 39020276, 2024).